IGHV3-48 (immunoglobulin heavy variable 3-48)
Description:
V region of the variable domain of immunoglobulin heavy chains that participates in the antigen recognition. Immunoglobulins, also known as antibodies, are membrane-bound or secreted glycoproteins produced by B lymphocytes. In the recognition phase of humoral immunity, the membrane-bound immunoglobulins serve as receptors which, upon binding of a specific antigen, trigger the clonal expansion and differentiation of B lymphocytes into immunoglobulins-secreting plasma cells. Secreted immunoglobulins mediate the effector phase of humoral immunity, which results in the elimination of bound antigens. The antigen binding site is formed by the variable domain of one heavy chain, together with that of its associated light chain. Thus, each immunoglobulin has two antigen binding sites with remarkable affinity for a particular antigen. The variable domains are assembled by a process called V-(D)-J rearrangement and can then be subjected to somatic hypermutations which, after exposure to antigen and selection, allow affinity maturation for a particular antigen.
Synonyms: IGHV348; VH
Tractability: Antibody: its Gene Ontology location is reachable by antibodies, with high confidence; UniProt places it where antibodies can reach, with medium confidence; UniProt predicts a signal peptide or a membrane-spanning region.
Gene: Immunoglobulin variable (V) gene on chromosome 14 (106,537,810 to 106,538,344, reverse strand). Ensembl gene ENSG00000211964.
Subcellular location: Secreted; Cell membrane
Pathways (Reactome):
Immune System: Antigen activates B Cell Receptor (BCR) leading to generation of second messengers; CD22 mediated BCR regulation; Classical antibody-mediated complement activation; FCERI mediated Ca+2 mobilization; FCERI mediated MAPK activation; FCERI mediated NF-kB activation; FCGR activation; Fc epsilon receptor (FCERI) signaling; Immunoregulatory interactions between a Lymphoid and a non-Lymphoid cell; Initial triggering of complement; Regulation of Complement cascade; Regulation of actin dynamics for phagocytic cup formation; Role of LAT2/NTAL/LAB on calcium mobilization; Role of phospholipids in phagocytosis
Disease: FCGR3A-mediated IL10 synthesis; FCGR3A-mediated phagocytosis; Potential therapeutics for SARS
Hemostasis: Cell surface interactions at the vascular wall
Vesicle-mediated transport: Scavenging of heme from plasma
Gene Ontology:
Molecular function: antigen binding
Biological process: immune response; immunoglobulin mediated immune response
Cellular component: extracellular region; plasma membrane
Homologues: Paralogues in human: IGHV3-21 (95% identical), IGHV3-7 (91% identical), IGHV3-74 (89% identical), IGHV3-23 (88% identical), IGHV3-11 (87% identical), IGHV3-13 (87% identical), IGHV3-64 (85% identical), IGHV3-66 (85% identical), IGHV3OR16-10 (85% identical), IGHV3OR16-13 (85% identical), IGHV3-30 (85% identical), IGHV3-33 (85% identical), and 65 more.
Diseases named in the same sentence as IGHV3-48 in open-access papers:
IGHV3-48 is named in the same sentence as 1 disease in open-access papers, as found by Europe PMC text mining. Sharing a sentence is not in itself a finding about the gene and the disease.
IGHV3-48 shares sentences with these, for which no sentence is quoted: asthma (1 paper).